SNORD116-16 (small nucleolar RNA, C/D box 116-16)
Synonyms: HBII-85-16
Gene: Small nucleolar RNA gene on chromosome 15 (25,082,768 to 25,082,859, forward strand). Ensembl gene ENSG00000207263.
Gene Ontology:
Biological process: RNA processing
Cellular component: nucleolus
Homologues: Orthologues: chimpanzee SNORD116 (100% identical), macaque SNORD116 (100% identical), guinea pig SNORD116 (92% identical), guinea pig SNORD116 (88% identical). Paralogues in human: SNORD116-17 (97% identical), SNORD116-19 (97% identical), SNORD116-24 (97% identical), SNORD116-14 (96% identical), SNORD116-15 (96% identical), SNORD116-18 (96% identical), SNORD116-20 (96% identical), SNORD116-21 (96% identical), SNORD116-22 (96% identical), SNORD116-23 (95% identical), SNORD116-12 (90% identical), SNORD116-11 (89% identical), and 20 more.